IDO1 (indoleamine 2,3-dioxygenase 1)
Diseases named in the same sentence as IDO1 in open-access papers (continued):
Sharing a sentence is not in itself a finding about the gene and the disease.
tumor (continued). "The tumor vessels may also block the activation of T-cells that are recruited to the tumor tissue by expressing inhibitory molecules such as PDL1 and IDO1 or directly induce T-cell apoptosis by expression of death-receptor family members including TRAIL or FASL." (PMID 26770016, 2015). "One of the strongest mediators of the tumor-induced immunosuppression is kynurenine, the product of tryptophan catabolism via tryptophan dioxygenase (TDO) and indoleamine 2,3-dioxygenase enzymes (IDO1 and IDO2), which are induced by interferon- γ (IFN-γ), nitric oxide (NO) and iron." (PMID 25955018, 2015). "Tryptophan catabolism is initiated by either indoleamine 2,3-dioxygenase (IDO-1/-2) or tryptophan 2,3-dioxygenase 2 (TDO2), resulting in biostatic tryptophan starvation and l-kynurenine production, which participates in shaping the dynamic relationship of the host’s immune system with tumor cells." (PMID 25881064, 2015). "Whereas IDO1 has been found in DC of tumor-draining lymph nodes, IDO1 could not be detected in regional lymph nodes of uteri of pregnant mice (P. Ack, Astrid Blaschitz, unpublished observations)." (PMID 24904580, 2014). "In none of the tumour cell lines, IDO1 protein expression was visualised without IFN-γ stimulation." (PMID 22108515, 2012). "Treatment of cancer patients with 1-D-MT has transcriptional effects that may promote rather than suppress anti-tumor immune escape by increasing IDO1 in the cancer cells." (PMID 21625531, 2011). "IDO-1-expression in tumor infiltrate was much higher (as compared to tumor cells); for 4 patients IHC-staining was not clearly detectable and of the 433 remaining patients, tumor immune infiltrate was IDO-1- for just 27 patients (6.2%), while 406 patients (93.8%) were IDO-1+." (PMID 40475772, 2025). "Enhanced FAO further amplifies IDO1 activity and Treg generation while shifting DC metabolism from glycolysis to oxidative phosphorylation to reinforce FAS, maintaining a balance between FAS and FAO, these adaptations may further contribute to tumor immune tolerance." (PMID 41430039, 2025). "However, high expression of IDO1 in HCC has also been shown to positively correlate with the number of CD8+ T cells, which indicates the presence of an anti‐tumour immune response, suggesting that IDO1 may be a favourable prognostic indicator for patients with HCC." (PMID 38935536, 2024). "Overall, apo-IDO1 is no longer just a transient conformation for heme cofactor acquisition that renders the protein enzymatically active, but represents a signaling molecule that could become an attractive target, especially in the tumor cell." (PMID 38333210, 2024). "Recent and growing evidence describes the existence of an apo-form of IDO1 (namely, the protein without heme cofactor and thus catalytically inactive) in the tumor microenvironment that could contribute to the immunoregulatory milieu via its non-enzymatic activity." (PMID 37122718, 2023). "Collectively, the available data suggested that epigenetic agents may prime the tumor microenvironment for immune checkpoint inhibition by triggering an IFN response, and that concurrent blockade of IFN-regulated resistance pathways via IDO1 could provide further clinical benefit." (PMID 37087488, 2023). "Thus, it is possible that IDO1 inhibitor treatment may ultimately lead to tumor vessel normalization, possibly providing an environment that is more amenable to conventional cancer therapy." (PMID 37182174, 2023). "Therefore, most of the patients who did not respond may not have tumour with IDO1 expression, thus skewing the clinical trial data." (PMID 37041200, 2023). "Thus, IDO1 was overexpressed in HCC tissues and could be further upregulated by HSV-1 treatment, which acted as a negative feedback mechanism of the immune system to limit HSV-1 replication in the tumor cells." (PMID 37296221, 2023).
tumor (continued). "The determination that there are at least two distinct mechanisms, (tryptophan depletion and kynurenine production), through which IDO1 can contribute to tumor-promoting inflammation increases the likelihood that IDO1 induction within a tumor may not always have the same biological consequences." (PMID 37182174, 2023). "In these experiments on the 4T1 tumor microenvironment, Ido1 could not be detected." (PMID 38201582, 2023). "Therefore, the inhibition of the non-enzymatic function of IDO1 could represent an alternative and promising approach in the anti-tumor immunotherapy." (PMID 37122718, 2023). "However, tumor cells and myeloid cells may express tryptophan 2,3-dioxygenase 2 (TDO2) and catabolize tryptophan via an alternative pathway that replaces or complements IDO1." (PMID 35571116, 2022). "In addition, immunofluorescence staining of tumor sections and corresponding quantitative analysis showed lower levels of IDO protein expression in 4T1 tumors with knockdown IDO1, while 4T1 tumors overexpressing IDO1 had higher levels of IDO protein expression." (PMID 36550159, 2022). "In addition to TMB, the composition of the tumor immune microenvironment (TIME) is another determinant of the response to immunotherapy, such as immunosuppressive cells (regulatory T cells and myeloid-derived suppressor cells) and cytokines (PGE2, IDO1, TGF-β, IL-10, etc.)." (PMID 35571116, 2022). "However, there is no targeting IDO1 drug applied to tumor treatment at present." (PMID 35563059, 2022). "Moreover, failure of these trials might be related to the lack of information about IDO1 expression and activity (kynurenine production) at the tumor site or systemically in the patients enrolled in the studies." (PMID 33924971, 2021). "Furthermore, IDO1 can be induced in endothelial cells, CAFs, and MSCs, which could participate in mediating an immunosuppressive TME, for instance, supporting cancer cells to evade tumor dormancy, impairing NK cell function, and inducing Treg expansion." (PMID 35003126, 2021). "It was also interesting that cells derived from the IDO1-negative biopsy secreted l-Kyn into the medium (E21-37, E11-21, E22-38), suggesting that the IHC staining of the tissue might not completely reflects the phenotype of cells that are present in tumor." (PMID 33922995, 2021). "Hence, upon immune-mediated inflammation, IDO1-negative tumor cells may upregulate IDO1 as resistance mechanism." (PMID 32117235, 2020). "Understanding recent clinical failures (e.g., IDO-1 antagonists) and the lack of correlation between PD-L1 expression and response to anti-PD-L1 highlight the need to define where particular drugs principally act—within the tumor or in a lymphoid organ/organoid." (PMID 30376867, 2018). "Thus, our use of HeLa tumor bearing models with IFN- γ treatment enabled us to confirm that [18F]IDO49 accumulation in the IFN-γ treatment tumor mouse was due to in vivo targeting of activated IDO1 expression rather than nonspecific retention." (PMID 28159919, 2017). "Indeed, there were more CD68-positive interstitial cells than IDO1-positive interstitial cells in RCC tissues, but virtually all the IDO1-positive interstitial cells localized to CD68+ areas, suggesting that IDO1 is present in inflammatory cells as well as in tumor and endothelial cells." (PMID 27572319, 2016). "However, those tumor cell lines without constitutive IDO1 expression could be invariably induced by certain stimuli such as IFN-γ, which is presumably analogous to actual state in vivo." (PMID 26895379, 2016). "However, Ido1+ tumors grew faster than Ido1− tumors in SCID/beige mice suggesting that some Ido1-controlled nonimmunological mechanisms may be involved in tumor cell growth regulation." (PMID 22654951, 2012). "Pathological identification and multiple immunofluorescence (mIF) determination of IDO1, KYN, and CD8+ T cells were performed after we collected normal mouse mammary glands and tumor‐bearing mouse mammary glands." (PMID 39661740, 2025).
tumor (continued). "Kynurenine is a stable intermediate of the kynurenine pathway, and increased levels (along with increased IDO1 and IDO2) are often detected within the tumor microenvironment, suggesting their negative impact on tumor growth." (PMID 40766249, 2025). "Notably, in this study, IDO1 expression was significantly reduced in tumors from mice treated with PTSO-pretreated hPBMCs, suggesting that this organosulfur compound may mitigate immune suppression and enhance anti-tumor immune responses, ultimately promoting tumor immunogenic cell death." (PMID 41010517, 2025). "When co‐cultured with immune cells, the combined action of 1‐MT and NO significantly inhibited IDO1‐mediated tryptophan metabolism to suppress KYN production, activate DCs, and enhance T‐cell proliferation, thereby reversing tumor immune suppression." (PMID 39661740, 2025). "In addition, selective IDO1 blockade may not be sufficient to alleviate tumor immunosuppression, and IDO2/TDO may serve as an enzyme with a potential compensatory mechanism to attenuate the efficacy of epacadostat, a possible reason for its failure of phase III clinical trial." (PMID 39585774, 2025). "Our results suggest a prognostic role of IDO-1 protein expression in NSCLC tumor and immune cells independent of EGFR, KRAS AND PD-L1 expression, and should be explored as a predictive biomarker in clinical studies with IDO-1 targeted therapies." (PMID 40475772, 2025). "IDO1 is primarily involved in regulating immune system responses and can be activated as negative feedback signaling by IFN-γ secreted by tumor-infiltrating lymphocytes, potentially contributing to tumor escape." (PMID 40287406, 2025). "On the other hand, IDO1 did not have a significant correlation with the other clinical and pathological characteristics of HNSCC patients, such as tumor grade, patient age, and patient gender." (PMID 38736462, 2024). "IDO1-negative carcinomas (n = 6): All IDO1-negative carcinomas were negative for ER-α and PR (IRS = 0, H-score = 0) but contained calponin-positive tumor cells." (PMID 39061522, 2024). "Nonetheless, the link between IDO1 and ESCC has not yet been fully elucidated, and further research on its role in the tumor microenvironment (TME) is needed." (PMID 39351094, 2024). "Because IDO1 was overexpressed in tumor cells but not in normal cells and supramolecular sensor was sensitive to the change of intracellular Trp concentration, this label-free method could precisely sort out tumor cells, avoiding the fussy pre-preparation and strict derivatizations." (PMID 38725031, 2024). "In fact, the non-enzymatic function of IDO1 is strictly related to the cell type populating the TME (i.e., tumor, immune, endothelial, and stromal cells)." (PMID 38333210, 2024). "Expression of IDO1 was not dose dependent and there was no significant increase in the CD8+ or CD4+ effector T cells or tumour-infiltrating leucocytes." (PMID 37041200, 2023). "IFN-γ can induce the expression of more than 200 genes, including those involved in immune evasion by tumor cells, such as PD-L1, PD-L2, CTLA-4, CIITA, non-classical MHC class Ib antigens, IDO1, and CXCL12." (PMID 37444608, 2023). "In contrast, IFNGR signaling in non-endothelial cells had the opposite effect of promoting tumor growth, consistent with the counter-regulatory production of IL6 elicited by IFNγ-mediated induction of IDO1." (PMID 37182174, 2023). "OCUM‐12‐CM did not induce ASPN, inflammatory cytokines, HIF‐1α, IDO‐1, or KYNU expression in NFs in vitro, suggesting changes to the tumor would reflect the effects of the coinjected CEFs." (PMID 34379869, 2022). "The expression levels of most immune suppressive genes in the tumor and inflammation areas of CSCC are not significantly higher than those in the non‐cancer samples, except for LGALS9 and IDO1." (PMID 35986392, 2022). "We further tested the effect of NNK on IDO1 in vivo by treating the mice with NNK and/or α-BGT for 3 months, at which time point no tumor was detected." (PMID 36068203, 2022).
tumor (continued). "BxPC-3, apart from being IDO1-positive cell line, is also not as aggressive as HPAF-II in tumor formation and growth in xenografts; this negates the need for early termination of the experiment and potential failure to detect any synergistic effect." (PMID 35997090, 2022). "Tumor densities of CD68+ and CD163+ cells were not different in C2D1 biopsies; neither those of DC-LAMP+, IDO1+, ICAM1+ or CD31+ cells (data not shown)." (PMID 35794623, 2022). "Indeed, recent findings suggest that IDO1 in tumor cells and non-tumor cells possess different functions that are non-overlapping, which may have bearing on difference in targetability with first generation of IDO1 inhibitors primarily focused on catalytic activity." (PMID 35173722, 2022). "The association between the COX2 and MDSCs/Treg attractants CXCL8 and CCL22, and suppressive factors IDO1 and IL-10 were observed exclusively after the BCG treatment of human BlCa tumor tissues, but not at baseline." (PMID 33809455, 2021). "IDO-1 is not expressed in metastatic renal cell carcinoma, but the expression of IDO-1 on tumor epithelial cells can be used to predict better PFS and therapeutic response to nivolumab." (PMID 34367975, 2021). "Notably, Tα1 did not induce IDO1 in the tumor microenvironment, but rather modulated the infiltration of T-cell subsets by inverting the ratio between CD8+ and Treg cells, an effect that may depend on Tα1 ability to regulate the differentiation and chemokine expression profile of DCs." (PMID 32817121, 2020). "This inhibitory function of IDO1 is thought to primarily be through the induction of T regulatory cells, although recent studies have described a novel function for IDO1 in inflammatory neovascularization, that could be just as, if not more, important in some tumor settings." (PMID 32973768, 2020). "In contrast, agonistic CD40 mAb therapy did not enhance IDO1 expression in CD45+ leukocytes, and the relative level of expression was considerably lower in leukocytes than what was observed in tumor endothelial cells after agonistic CD40 mAb therapy." (PMID 32231867, 2020). "The tumor studies with Ifnar1ΔIEC mice and ISS DNA-treated organoids suggest that Ido1 is not induced by type I IFN or TLR9 signaling." (PMID 32444775, 2020). "Unlike IDO1, the real IDO2 cellular function is poorly understood even today, in both normal and tumor cells." (PMID 32536910, 2020). "While previous studies have shown that IDO can be expressed by some mucosal epithelial and tumor cells, we found that in ECC1 culture alone, IDO1 expression levels were not detectable in response to C. trachomatis." (PMID 30832593, 2019). "It was determined that IDO1 and CSE were expressed in both tumor tissues (Tumor, T-) and adjacent non-neoplastic tissues (Liver, L-) of nine HCC patients." (PMID 30777103, 2019). "However, in a subset of tumors IDO1 is expressed by cancer cells in the absence of any inflammation indicating that it may be the result of oncogenic events and may contribute to escape of tumor by immunosurveillance by preventing T-cell infiltration." (PMID 30150994, 2018). "Tumor-intrinsic constitutive IDO1 expression might contribute to tumoral immune resistance by preventing T-cell infiltration, a mechanism conceptually different from adaptive resistance, where IDO1 expression would represent a negative feedback mechanism induced by the T-cell response." (PMID 25691885, 2015). "A high level of immune cell infiltration is observed in EBV positive (e.g. F8) but not the tumor grade matched EBV negative sample, A15 with a high proportion of the immune cells in F8 showing intense IDO1 staining." (PMID 23671415, 2013). "As in the pT1-4N1Mx subgroup only three tumours showed defective MMR protein expression, no statistical analysis was conducted in search for a possible correlation between IDO1 and MMR protein expression." (PMID 22108515, 2012).
tumor (continued). "In conclusion, IDO1 is expressed in CRC cells upon IFN-γ stimulation, and IDO1 expression at the tumour invasion front, but not in the centre of the tumour, is an independent prognostic factor in the pT1-4N1Mx-staged CRC." (PMID 22108515, 2012). "Not all cancers exhibit high levels of IDO1 or TDO2 expression, and the effectiveness of KYN pathway inhibitors may vary depending on tumor type and microenvironment." (PMID 39997327, 2025). "Our data demonstrated that the non-enzymatic IDO1 conformation could undergo tyrosine phosphorylation by Src kinase, which is constitutively activated in the FTC-133 tumor." (PMID 41262240, 2025). "Inhibitors of the IDO1‐KYN‐AHR pathway have been shown to alleviate the negative effects of Carboxyamidotriazole, a chemotherapeutic agent, against CD8+ T cells and produce supplementary useful pre‐tumour immunological effects." (PMID 38935536, 2024). "Interestingly, combinatorial inhibition of IDO1, IDO2, and TDO2 (together thought to be the predominant rate-limiting enzymes for the kynurenine pathway) did not impact tumor viability in patient derived GBM cells." (PMID 36900311, 2023). "In this study, we found that HSV-1 treatment could lead to up-regulation of IDO1 expression in HCC cells, which further acted as a negative feedback mechanism of the immune system to limit HSV-1 replication in tumor." (PMID 37296221, 2023). "On the other hand, mice that did not receive donor leukocyte infusion did not express IDO1 and IFN‐γ, implying that IDO inhibition can be advantageous for anti‐tumour therapy when used in conjunction with reduced‐intensity allogeneic haematopoietic stem cell transplant with donor leukocyte infusion." (PMID 37644823, 2023). "Although there are no previous reports suggesting that IDO1 may shape the cancer immune landscape in the TME and promote tumor progression by OS-derived exosome miRNAs, the significance of IDO1 in OS has been described earlier." (PMID 37284323, 2023). "Tumor-derived IL-6 phosphorylates STAT3 and stimulates two noncanonical NF-kB subunits, p52 and RelB to form a dimer that directly binds to the promoter of IDO1, then drives the expression of IDO1 in MDSCs." (PMID 35681736, 2022). "IDO‐1 and KYNU expression did not overlap with α‐SMA+ CAFs, and they were also mainly detected in the stromal cells, especially at the invading edge of the tumor periphery." (PMID 34379869, 2022). "IDO‐1, KYNU, PAPP‐A, and IL‐1B were not upregulated in CEF‐CM‐treated CAFs, suggesting that CEFs do not amplify pre‐existing CAF function, but that newly differentiated CEFs can promote tumor progression." (PMID 34379869, 2022). "The amplification of genes such as COL5A1, IDO1, and GOLIM4 were in accordance with their higher expression in tumor samples, whereas no significant change of protein or phosphorylation levels was observed for genes with genomic amplification, such as CD4, CD7, LIME1, UNC93B1, C1S, C1R, or C8G." (PMID 34400640, 2021). "Nevertheless, such MSI+ CYT-high tumor cells are not effectively eliminated by the immune system, due to the increased levels of several immune-inhibitory checkpoint molecules, such as PD-L1, PD-L2, CTLA-4, LAG3, TIGIT, IDO1 and VISTA." (PMID 31429779, 2019). "Therefore, the feedback of IDO1 to the CD8+ T cell response will be impaired, and the number of CD8+ T cells in the tumor microenvironment will not decrease." (PMID 31391111, 2019). "Inhibitors of the IDO1-Kyn-AhR pathway could abolish the negative effects of CAI on CD8+ T cells and result in complementary and beneficial anti-tumor immune effects." (PMID 31511064, 2019). "Neither the IDO1 inhibitor methyl-thiohydantoin-DL-tryptophan (MTH-trp) nor IFNα alone inhibited RENCA tumor growth, however the combination of MTH-trp and IFNα reduced tumor growth compared to IFNα." (PMID 27572319, 2016).